GDNF (glial cell derived neurotrophic factor)
Diseases named in the same sentence as GDNF in open-access papers (continued):
Sharing a sentence is not in itself a finding about the gene and the disease.
acromegaly (3 papers, 2020 to 2024). Acromegaly is an acquired disorder related to excessive production of growth hormone (GH) and characterized by progressive somatic disfigurement (mainly involving the face and extremities) and systemic manifestations. "Within the adenopituitary, somatotrophs express both RET and GFRα1, together with GDNF and this is maintained in somatotroph-derived pituitary tumors causing acromegaly." (PMID 33071961, 2020). "Moreover, GFRα1 expression together with its ligand GDNF-remains relevant in somatotroph derived tumors causing acromegaly." (PMID 33071961, 2020). "Somatotroph adenomas from pituitary-specific Aip-knockout mice overexpress the RET-ligand GDNF, therefore, upregulating the survival pathway." (PMID 34588620, 2021). "It is known that GDNF is expressed by normal somatotrophs together with GFRα1 and its expression is preserved in somatotroph adenomas." (PMID 33071961, 2020). "Somatotroph adenomas from patients with or without AIP mutation abundantly express GDNF, but AIP-mutated tissues have less CDKN2A-ARF expression." (PMID 34588620, 2021). "In acromegaly, every gene involved in the two RET pathways—particularly glial cell-derived neurotrophic factor (GDNF)—is specifically enriched." (PMID 39194755, 2024). "We performed immunohistochemistry for RET (total RET, HPA008356), GDNF and GFRα1 comparing five sporadic (Sp GH) and five AIP+ somatotroph adenomas." (PMID 34588620, 2021). "One possible treatment for resistant acromegaly (in general) is Sorafenib, an RET inhibitor, which acts by blocking GDNF/AKT serine/threonine kinase 1 survival action through protein kinase AMP-activated catalytic subunit alpha 2 and prevents cell death without changing the RET apoptotic pathway." (PMID 39194755, 2024).
Atrophy (3 papers, 2022 to 2024). Any weakening or degeneration, especially through lack of use. "In other animal studies, variations in the GDNF gene can also cause renal abnormalities, containing kidney atrophy, cortical cysts, and unilateral dysplasia." (PMID 36408280, 2022). "GDNF overexpression in 3xTg-AD mice has shown cognitive improvements with concomitant BDNF up-regulation, suggesting a synergistic neuroprotective effect against neuronal atrophy." (PMID 38067101, 2023). "The manuscript focuses only on PSP-P and PSP-RS, however, based on the results obtained, it could be assumed that in CSF, GDNF level increases in proportion to the severity of atrophy regardless of clinical phenotype." (PMID 38307947, 2024).
Azoospermia (3 papers, 2015 to 2025). Absence of any measurable level of sperm,whereby spermatozoa cannot be observed even after centrifugation of the semen pellet. "The ultrastructural features of SCs and the release of mitogens from these cells (e.g. GDNF, SCF) differ between patients with abnormal spermatogenesis (non-obstructive azoospermia) and those with preserved spermatogenesis (obstructive azoospermia)." (PMID 36523595, 2022).
behavioral disorders (3 papers, 2016 to 2022). "Next, we showed that overexpressing GDNF by intrathecal injection of LV-GDNF was effective at improving morphine-induced behavioral disorders." (PMID 36138924, 2022).
bone cancer (3 papers, 2022 to 2023). A primary or metastatic malignant neoplasm affecting the bone or articular cartilage. "Our results show that GDNF could delay morphine analgesic tolerance and alleviate bone cancer-induced mechanical and thermal hyperalgesia in rats." (PMID 36138924, 2022). "In an animal model of bone cancer pain, RET can bind to the ligand GDNF to activate the downstream ERK signaling pathway, and promote sensitization of DRG neurons." (PMID 37250405, 2023). "Our previous study showed that spinal GDNF was downregulated after rats developed BCP, and the overexpression of GDNF could alleviate bone cancer pain, which suggests that spinal GDNF acts as an important regulator in the development of BCP." (PMID 36138924, 2022).
brain infarction (3 papers, 2016 to 2021). Tissue necrosis in any area of the brain, including the cerebral hemispheres, the cerebellum, and the brain stem. "Brain concentration of GDNF and reduction of cerebral infarction following intravenous administration to mice." (PMID 26840305, 2016).
Cachexia (3 papers, 2022 to 2023). Severe weight loss, wasting of muscle, loss of appetite, and general debility related to a chronic disease. "The GDF-15 has been shown to signal through the glial cell-derived neurotrophic factor (GDNF) family receptor α-like (GFRAL), which is solely expressed in the human brain stem and is associated with GDF-15-mediated anorexia and cachexia." (PMID 37905271, 2023).
diabetic retinopathy (3 papers, 2021 to 2025). "The expression of GDNF restricts vascular permeability by regulating the function of capillary endothelial tight junctions, thereby influencing the progression of diabetic retinopathy." (PMID 38606083, 2024). "Although the exact implications for diabetic retinopathy remain open at this point, the loss of a SPP1, which has been described to rescue photoreceptors and to be induced by neuroprotective factor GDNF, is an important finding of our study and deserves further investigation in our opinion." (PMID 34046254, 2021). "Glial cell line-derived neurotrophic factor (GDNF) and neurturin facilitate glutamate uptake by retinal cells, which may help mitigate apoptosis and reflect a compensatory mechanism in response to neuroinflammation and neuronal damage typically seen in diabetic retinopathy." (PMID 41153721, 2025).
meningitis (3 papers, 2017 to 2022). A disorder characterized by acute inflammation of the meninges of the brain and/or spinal cord. "Conversely, GDNF was specifically higher in the CSF of patients with meningitis (median: 14 pg/mL; IQR 14–50.3 pg/mL)." (PMID 35458486, 2022). "GDNF expression decreased in the hippocampus of the meningitis/saline and meningitis/tamoxifen groups when compared with the control group (P < 0.05)." (PMID 29200666, 2017). "In the hippocampus, there were effects for meningitis (F = 50.64; P < 0.001) for treatments (F = 29.84; P < 0.001), as well as interaction (F = 6.65; P = 0.005) in the GDNF expression." (PMID 29200666, 2017). "Meningitis group showed decreased expression of BDNF and GDNF in the hippocampus while lithium reestablished the neurotrophin expression." (PMID 29200666, 2017).
motor neuron disease (3 papers, 2013 to 2023). "This is in accord with a previous study which found higher GDNF immunoreactivity in the spinal cord of the motor neuron disease mouse model after intraspinal MSC injection." (PMID 24069165, 2013).
multiple system atrophy (3 papers, 2021 to 2024). Multiple system atrophy (MSA) is a neurodegenerative disorder characterized by autonomic failure (cardiovascular and/or urinary), parkinsonism, cerebellar impairment and corticospinal signs with a median survival of 6-9 years. "Furthermore, according to patient samples with multiple system atrophy, GDNF is largely produced and localized in Purkinje cells of the cerebellum." (PMID 36902541, 2023). "Decreased levels of neurotrophic factors such as glial derived neurotrophic factor (GDNF), brain derived neurotrophic factor (BDNF), and insulin-like growth factor 1 (IGF1) have been identified in human brains with multiple system atrophy and in mouse models." (PMID 34512258, 2021).
pheochromocytoma (3 papers, 2015 to 2019). "Considering the important role of RET in pheochromocytoma development, researchers further suggested that mutations in GDNF affecting its interaction with RET may be also associated with the disease." (PMID 28187001, 2017). "However, whereas somatic mutations in the GDNF gene have been found in a few cases of pheochromocytomas, these are also present in healthy individuals." (PMID 28187001, 2017). "Next, we tested the bio-functionality of NGF in a rat pheochromocytoma cell line (PC12) and the bio-functionality of GDNF in an organotypic spinal cord culture." (PMID 26388717, 2015).
progressive supranuclear palsy (3 papers, 2016 to 2025). A rare late-onset neurodegenerative disease characterized by supranuclear gaze palsy, postural instability, progressive rigidity, and mild dementia. "In the present study, the GDNF concentrations in CSF and serum were investigated among patients with Progressive Supranuclear Palsy (PSP)." (PMID 38307947, 2024).
renal hypoplasia (3 papers, 2018 to 2021). Renal hypoplasia is a developmental anomaly in which one or both kidneys (unilateral or bilateral renal hypoplasia, respectively) have a deficit in the number of nephrons and may be small. "Other investigators have shown that null mutations of either c-Ret or Gdnf block initial UB outgrowth from the nephric duct, leading to renal agenesis in mice; decreased activity of GDNF/c-Ret signaling leads to renal hypoplasia in both mice and humans." (PMID 35076510, 2021). "This is supported by our genetic experiments in which lowering UB-expressed Wnt11 expression in the Gdnfhyper/hyper background improved NP maintenance and differentiation, but failed to fully rescue the renal hypoplasia caused by the excess GDNF." (PMID 34032268, 2021). "We hypothesized that persistent NPCs in postnatal Gdnfhyper/hyper kidneys could either result from general compensatory mechanisms provoked by UB branching defects leading to renal hypoplasia or alternatively derive from the GDNF-specific effects on the NP population." (PMID 34032268, 2021).
seminoma (3 papers, 2012 to 2013). A radiosensitive malignant germ cell tumor found in the testis (especially undescended), and extragonadal sites (anterior mediastinum and pineal gland). "GDNF-induced seminoma cell migration appears to be mediated by the Src and MEK pathways but not by the PI3K pathway." (PMID 23613711, 2013). "Intriguingly, GDNF has also been demonstrated to stimulate chemotaxis in both normal, transformed cells and seminoma cells." (PMID 23613711, 2013). "Taken in conjunction with the finding that GDNF overexpression in mice leads to the formation of seminomas in advanced age, it is conceivable to suggest that changes in somatic cells in the testis can lead to the deregulation of the SSC somatic niche." (PMID 23519268, 2013). "As GDNF is able to induce the directional migration of normal and transformed cells, including seminoma cells, we hypothesized that undifferentiated spermatogonia migrate in response to a GDNF gradient." (PMID 23613711, 2013). "On the other hand hyperactivation of RET in Ret+/+ mice by overexpressing glial derived neurotrophic factor (GDNF), the major ligand of RET in the testis, results in germ cell tumors that are seminoma-like and led to disruption of normal spermatogenesis." (PMID 22359510, 2012). "Interestingly, GDNF does not affect cell survival and proliferation in the seminoma cell line, but it does induce directional migration and promotes invasive behavior." (PMID 23613711, 2013).
Strabismus (3 papers, 2018 to 2024). A misalignment of the eyes so that the visual axes deviate from bifoveal fixation. "The question of specificity of this GDNF treatment and the subsequent appearance of strabismus is a commonly raised concern." (PMID 32681083, 2020). "Sustained treatment with GDNF to one medial rectus muscle in infant monkeys resulted in the development of a significant strabismus, which at 3 months averaged 10.58° of misalignment in the 6 treated infant monkeys." (PMID 32681083, 2020). "The development of strabismus after 3 months of GDNF treatment in infant monkeys supports the potential role of GDNF in the onset and/or maintenance of strabismus." (PMID 32681083, 2020). "At the 6 month time point, 3 months post -GDNF treatment, a micro-strabismus was maintained in all 3 monkeys, with a mean of 9.67° ± 1.68° when the final 3 mean angles for each monkey were averaged." (PMID 32681083, 2020). "Whatever the exact mechanism, the end result was that 3 months of sustained GDNF treatment resulted in a strabismus in these infant monkeys." (PMID 32681083, 2020). "A second pattern was seen in 2 of the 9 infants treated with either IGF-1 or GDNF studied thus far, where there was a relatively rapid decrease in their exotropia within the first 2–4 weeks, followed by an increase in strabismus angle between 2 and 3 months." (PMID 32681083, 2020). "The ability of 3 months of sustained release GDNF treatment to produce significant and maintained strabismus in infant monkeys is further evidence for its potential impact in maintaining normal EOM function and eye alignment." (PMID 30142211, 2018). "Our preliminary study showed that GDNF treatment of infant monkey EOM resulted in the development of strabismus." (PMID 30142211, 2018). "Our preliminary data showed that 3 months of unilateral, sustained GDNF treatment in infant monkey medial and lateral rectus muscles resulted in the development of strabismus." (PMID 30142211, 2018). "Together, these studies suggest that alterations in GDNF signaling play a role in the etiology of childhood onset strabismus." (PMID 30142211, 2018). "By 2 and 5 months, the infant-associated exotropia seen in all the infant non-human primates was reduced to 1.6° and 3.5°, angles below what is defined as strabismus, adding support to the data showing maintained or induced eye misalignment in the GDNF-treated infant monkeys." (PMID 32681083, 2020). "This study sheds light on potential mechanisms by which alteration in GDNF signaling might produce strabismus." (PMID 30142211, 2018). "The ability of sustained treatment of a single extraocular muscle with glial cell line-derived neurotrophic factor (GDNF) to produce a strabismus in infant non-human primates was tested." (PMID 32681083, 2020). "Sustained treatment of an adult strabismic monkey with IGFI resulted in a significant improvement in eye alignment, and sustained treatment with either IGF1 or glial derived neurotrophic factor (GDNF) during the first 3 months of life in nonhuman primates resulted in development of strabismus." (PMID 39330989, 2024). "Decreased levels of CNTF, GDNF, as well as altered levels of IGF binding proteins, which are inhibitory in function, shown in the microarray studies suggest that increasing the levels of a single neurotrophic factor is likely to be insufficient to generate or treat a large angle strabismus." (PMID 32681083, 2020).
Type 2 diabetes (3 papers, 2021 to 2024). "It has also been found that the concentration of GDNF in the serum of patients with type 2 diabetes is significantly reduced compared with those with normal glucose tolerance." (PMID 34193268, 2021).
adenoid cystic carcinoma (2 papers, 2021 to 2024). A malignant tumor arising from the epithelial cells. "Nerve growth factor signals, such as those of glial-derived neurotrophic factor (GDNF) and its receptors, are known to be involved in PNI of adenoid cystic carcinoma." (PMID 33628594, 2021). "Also, glial cell-derived neurotrophic factor (GDNF)-RET signaling pathway activation stimulates both MMP-2 and MMP-9 expression in adenoid cystic carcinoma (ACC) of the salivary glands." (PMID 39906323, 2024).
alcohol (2 papers, 2023 to 2025). "To date, numerous animal and human research have been undertaken to investigate the impact of GDNF on alcohol misuse." (PMID 40371361, 2025). "It is assumed that epigenetic regulation of growth factors, such as glial cell line-derived neurotrophic factor (GDNF) and BDNF, may contribute to the development of alcohol dependence." (PMID 36834747, 2023).
astroglioma (2 papers, 2017). "The effects of Egr-1 overexpression on the binding of Egr-1 and RNA POL II to GDNF promoter II and GDNF transcription were examined by ChIP-PCR and real-time PCR in C6 astroglioma cells." (PMID 28187447, 2017). "However, three sites in β-catenin (i.e., Tyr489, Tyr654, and Ser33/37/Thr41) obviously decreased phosphorylation levels when malignant astroglioma cell was stimulated by high GDNF which might suggest a positive feedback effect on the activity of cadherin/catenin core complex." (PMID 28212546, 2017).
cerebellar degeneration (2 papers, 2017 to 2021). Degeneration of the cerebellum. "Glial cell derived neurotrophic factor (GDNF) has a short in vivo half-life, but delivery in PLGA microparticles increased half-life, improved motor function and dopaminergic neuron restoration, with no adverse effects on immunogenicity, cerebellar degeneration, or weight loss in vivo." (PMID 34113606, 2021).
cerebral artery occlusion (2 papers, 2018 to 2022). "NSC-CM include neurotrophic factors, like GDNF and BDNF, while BDNF or GDNF was confirmed to exert antiapoptotic effect after transient middle cerebral artery occlusions in rats." (PMID 29765412, 2018).
Cirrhosis (2 papers, 2022 to 2024). A chronic disorder of the liver in which liver tissue becomes scarred and is partially replaced by regenerative nodules and fibrotic tissue resulting in loss of liver function. "A total of 735 patients from two medical centers (385 CHB patients and 350 healthy controls) were included to determine the association of serum and tissue GDNF levels with biopsy-proven cirrhosis." (PMID 35855954, 2022). "The diagnostic accuracy of serum GDNF (sGDNF) was estimated and compared with other indices of cirrhosis." (PMID 35855954, 2022). "We assessed the potential of glial cell line-derived neurotrophic factor (GDNF) as a useful biomarker to predict cirrhosis in chronic hepatitis B (CHB) patients." (PMID 35855954, 2022). "In this study, we showed that patients with biopsy-proven cirrhosis and fibrosis demonstrated higher serum protein and tissue mRNA levels of GDNF." (PMID 35855954, 2022). "In culture, exogenous GDNF activates hepatic stellate cells (the liver-resident mesenchymal cells that differentiate to myofibroblasts) to produce an extracellular fibrous matrix that culminates in hepatic cirrhosis." (PMID 38339124, 2024). "Patients with fibrosis/cirrhosis (METAVIR stage F1–F4, N = 318) had higher serum GDNF (sGDNF) levels (28.4 pg/ml (IQR: 26.2, 31.6)) than patients without fibrosis (11.6 pg/ml (IQR: 7.2, 21.1)) (healthy controls and METAVIR stage F0, N = 376) (p < 0.001)." (PMID 35855954, 2022).
colon adenocarcinoma (2 papers, 2012 to 2022). "In a recent study of colon adenocarcinoma associated with diffuse ganglioneuromatosis, a glial cell line-derived neurotrophic factor (GDNF) and its receptor components were identified." (PMID 22978818, 2012).
colon cancer (2 papers, 2017 to 2018). "GDNF has been shown to enhance the migration of colon cancer cells by increasing vascular endothelial growth factor (VEGF)/VEGF receptor interactions, which are mainly regulated by the p38, phosphatidylinositol 3-kinase/Akt, and hypoxia-inducible factor 1α signaling pathways." (PMID 30220972, 2018). "GDNF also interacts with VEGF-VEGFR1 to increase human colon cancer cell motility." (PMID 29088765, 2017).
delirium (2 papers, 2024 to 2025). A disorder characterized by confusion; inattentiveness; disorientation; illusions; hallucinations; agitation; and in some instances autonomic nervous system overactivity. "Moreover, mDNA in the neurotrophic genes of GDNF in both the brain and blood increases with age, especially among delirium patients." (PMID 38928583, 2024).
Gait ataxia (2 papers, 2014). A type of ataxia characterized by the impairment of the ability to coordinate the movements required for normal walking. "Exogenous trophic factors (GDNF and/or IGF-1) can delay the onset of hereditary Purkinje cell degeneration and gait ataxia in shaker mutant rats characterised by spatially restricted degeneration of cerebellar Purkinje neurons from adult-onset heredodegeneration." (PMID 26331034, 2014).